MTOR (mechanistic target of rapamycin kinase)
Diseases named in the same sentence as MTOR in open-access papers (continued):
Sharing a sentence is not in itself a finding about the gene and the disease.
cancer (continued). "This, in turn, resulted in the deactivation of the AKT/mTOR signaling pathway, eventually leading to reduced proliferation, migration, and invasion of cancer cells." (PMID 38773612, 2024). "Role of PDE6H in cancer cell growth and metabolism was studied through the effects of its depletion on levels of cell cycle controllers, mTOR effectors, metabolite levels, and metabolic energy assays." (PMID 38350962, 2024). "The mammalian target of rapamycin (mTOR) is a critical signaling hub for sustaining cancer survival." (PMID 39513392, 2024). "The PI3K/AKT/mTOR signalling pathway contributes to the development of cancers by regulating HIF-1a activation; blocking the PI3K/AKT pathway inhibits HIF-1a expression and promotes its degradation." (PMID 38893278, 2024). "Given the diverse roles of p62 and mTOR across different cancer contexts and treatment scenarios, further investigations into their prognostic utilities and therapeutic potential is advisable." (PMID 38560690, 2024). "Lactate is also known to activate the mTORC1 complex in cancer cells, and the activation of mTOR signals via HIF1α, initiates VEGF expression in FCDIIb." (PMID 39483922, 2024). "The simultaneous inhibition of EGFR and RAS/mTOR was demonstrated to provide a synergistic antitumor effect in various human cancers." (PMID 38396679, 2024). "The mTOR complex has been portrayed as a nutrient receptor in cancer metabolism, in particular for nutrients such as glucose, amino acids, nucleotides, fatty acids and lipids as well as growth factors and other stressors." (PMID 38539200, 2024). "Nsp1 expression in cancer cells resulted in the down-regulation of several oncogenic or progrowth signaling pathways, including the mTOR and MAPK pathways, and up-regulation of the DNA damage marker p-H2AX, consistent with its anticancer activity." (PMID 39161732, 2024). "Arbutin has been shown to suppress the proliferation of certain cancer cells by downregulating the AKT/mTOR signaling pathway." (PMID 39628695, 2024). "The constitutive activation of the PI3K/AKT/mTOR pathway reduced the efficacy of OXY in cancer cells, rendering the TOV21G cells resistant to its effects on cell apoptosis induction." (PMID 39334906, 2024). "The targeting of mTOR by miRNAs has been shown to influence the radiosensitivity of cancer cells, suggesting a potential therapeutic strategy for enhancing the effectiveness of RT in cancer treatment." (PMID 38965615, 2024). "The increase in PTEN expression led to the silencing of the signaling pathways PI3K, AKT, and mTOR in cancer cells." (PMID 39125943, 2024). "Enrichment analysis of the target genes identified several tumor-related pathways, including Proteoglycans in cancer, the mTOR signaling pathway, and the FoxO signaling pathway." (PMID 39169938, 2024). "In recent studies, miRNAs such as miRNAs − 100, miRNAs − 99a, and miRNAs − 21 have demonstrated their ability to regulate mTOR signaling and influence the radiosensitivity of cancer cells, providing a potential avenue for therapeutic intervention." (PMID 38965615, 2024). "This anti-cancer activity is attributed to its inhibition of the mTOR pathway, which is frequently dysregulated in cancer." (PMID 39858295, 2024). "This can then lead to PI3K/AKT/mTOR phosphorylation, which helps cancer cells resist apoptosis, increasing cell survival so cancer can progress." (PMID 39839775, 2024). "The activation of the PI3K/Akt/mTOR signalling pathway by insulin and IGFs is recognised for its role in propelling cancer progression." (PMID 39301314, 2024). "Upon activation, Akt phosphorylates multiple substrates that enhance cancer progression, particularly through the mechanistic target of rapamycin (mTOR)." (PMID 39596452, 2024).
cancer (continued). "The PI3K/AKT/mTOR signaling pathway is one of the most activated signaling pathways in cancer, promoting tumor development." (PMID 38610001, 2024). "PI3K and mTOR pathway activation happens in many cancers; so, targeting S6 is a potential strategy for cancer treatment." (PMID 38473222, 2024). "In breast cancer, elevated BCAT1 levels promote mitochondrial biogenesis in an mTOR-dependent manner, which supports cancer proliferation." (PMID 39795113, 2024). "The interplay between the upstream and downstream components of the PI3K/AKT/mTOR signaling pathway is a significant regulator of cancer cell glycolysis." (PMID 39479443, 2024). "As such, some of the major signaling pathways regulated by PP2A are the PI3K-AKT, Wnt, mTOR, and MAPK, accounting for the association between PP2A dysfunction and cancer progression." (PMID 38184584, 2024). "MTOR plays a crucial role in tumor progression, and mTOR inhibitors have been employed in clinical cancer treatment." (PMID 38183097, 2024). "Some reports have shown that dapagliflozin and canagliflozin are able to inhibit the cancer cell proliferation blocking cell cycle in the G1/G0 phase by targeting AMPK/mTOR and inducing apoptosis." (PMID 39201363, 2024). "This study aimed to investigate the differential expression of genes and miRNAs involved in the PI3K/AKT/mTOR signaling pathway, a critical regulator of cancer progression." (PMID 39850811, 2024). "Swainsonine has been demonstrated to inhibit the PI3K/AKT/mTOR signaling pathway, leading to a reduction in the proliferation and increase in the death of human cancer cells." (PMID 39057437, 2024). "Flavonoids are involved in the modulation of Akt/PI3K/mammalian target of rapamycin (mTOR) pathway that stimulates and regulate the growth and development of cancer cells." (PMID 39063337, 2024). "Excitation of PI3K/AKT/mTOR signal path contributes to cancer progression or resistance to antitumor therapy." (PMID 38555280, 2024). "The mTOR and Ras/Raf/ERK/MEK (MAPK) are major pathways in cancer therapeutics and are commonly activated by mutation." (PMID 38674064, 2024). "This study delves into the intricate connection between the multifaceted functions of Rheb1 in neurons and cancer, with a specific focus on the mTOR pathway." (PMID 38338768, 2024). "Development of carriers for intracellular delivery of small molecule drugs, such as PI3K/mTOR inhibitors, is urgently needed to reduce the frequency of cancer treatment failure due to adverse effects." (PMID 40115434, 2024). "A restricted diet is strongly linked to slowing cancer progression through mechanisms involving the IGF-1 pathway and mTOR activation." (PMID 39596005, 2024). "Dysregulation of cancer-critical genes leads to mTOR hyperactivation, which in turn, increases the translation of pro-oncogenic proteins that directly affect cellular processes such as cell growth, migration, and de novo blood vessel formation." (PMID 38892329, 2024). "mTOR signaling is commonly activated in tumors and controls cancer cell metabolism by altering expression or activity." (PMID 38654380, 2024). "In cancer immunotherapy, the PI3K/AKT/mTOR signaling pathway is closely linked to the expression of PD-L1." (PMID 38616230, 2024). "By inhibiting mTOR, Rapamycin slows cancer cell growth, reduces angiogenesis, and dampens immune evasion, resulting in smaller tumors and slower progression." (PMID 39772235, 2024). "The inhibition of the mammalian target of rapamycin (mTOR) pathway by metformin suppresses cancer progression and angiogenesis." (PMID 38474224, 2024). "Metformin has demonstrated its ability to inhibit mTOR activation in several cancer types, including thyroid, breast, lung, and leukemia." (PMID 39193327, 2024). "The involvement of the PI3K/AKT/mTOR pathway in malignant tumor behaviors such as proliferation, migration, and stemness has been well documented 16-18." (PMID 39668819, 2024).
cancer (continued). "PI3K/AKT/mammalian target of rapamycin (mTOR) pathway is another critical intracellular signaling pathway that is frequently dysregulated in cancer, promoting cell growth, survival, and metabolism." (PMID 39370455, 2024). "Key enzymes involved in glycolysis and glucose uptake are inhibited by QUE’s metabolic effect on cancer through disruption of the PI3K/Akt/mTOR pathways." (PMID 39273552, 2024). "Frequent alterations in mTOR have been noted to play a significant role in tumorigenesis, distant metastasis, and drug resistance in human cancers such as those of the lung, breast, liver, kidney, pancreas, and prostate." (PMID 39201363, 2024). "Studies have shown that combining agents that target mTOR signaling with those that induce autophagy inhibition results in enhanced tumor control compared to that achieved with any single agent in multiple cancer types 37-39." (PMID 38356720, 2024). "Further, UA or OA + UA treatment of BrCa cells caused an inhibition of PI3 kinase-mediated phosphorylation of Akt/mTOR, the key pathways that regulate cancer cell survival, metabolism, and proliferation." (PMID 39409987, 2024). "Obviously, the mTOR inhibition per se is not sufficient for the GRN rearrangement, it is likely that the etiology of latent cancer cells is based on the synergy of external stimuli and mTOR blockage." (PMID 38418814, 2024). "I3C affects several signaling pathways and target molecules, such as PI3K/Akt/mTOR and NF-κB, that control cell division, apoptosis, and angiogenesis in various recognized cancers, including UFs." (PMID 38542717, 2024). "The activation of the PI3K/AKT/mTOR pathway plays an important role in the development of various cancers and resistance to cancer treatments." (PMID 38396649, 2024). "In this context, DHA significantly blocked cancer stem‐like cells (CLCSs) properties in CRC through inhibition of Akt/mTOR signaling." (PMID 39723045, 2024). "Our findings indicate that silibinin effectively suppresses the expression of EGFR mRNA, a crucial compound in the PAM signaling pathway, along with several downstream genes, including PI3K, AKT-1, PTEN, and mTOR mRNAs, in cancer cells." (PMID 38504785, 2024). "PLD molecular isoforms and their hydrolysis product phosphatidic acid (PA) can activate the mTOR signaling pathway in several ways, enhancing protein synthesis in cancer cells and promoting cancer cell survival." (PMID 39839794, 2024). "In cancer, mTOR levels are often elevated and have been observed to stimulate aerobic glycolysis via the induction of pyruvate kinase isoenzyme 2 (PKM2) and other glycolytic enzymes." (PMID 38255314, 2024). "Next, to explore the potential molecular effectors of the miR-617/DDX27 axis, we chose to examine the PI3K/AKT/MTOR pathway as it is one of the most frequently activated pathways in cancers, including OSCC." (PMID 38939334, 2024). "Taken together, our two independent strategies pointed towards seven core pathways including ribosome, spliceosome, transcription, proteasome, cell cycle, Akt-mTOR, and tight junction, inhibition of which sensitized cancer cells to various drugs." (PMID 39769257, 2024). "Multiple critical regulators originating from the PI3K/AKT/mTOR pathway inter-regulate and activate with ncRNA, resulting in their involvement in cancer progression." (PMID 39119480, 2024). "Metformin treatment has been shown to significantly increase the expression of REDD1, which in turn inhibits mTOR, thereby affecting the further advancement of cancer, such as that seen in glioma." (PMID 38891882, 2024). "High-dose rapamycin is being used in clinical trials for cancers with aberrant activation of mTOR and its signaling pathways 20-23." (PMID 38725843, 2024). "The aberrant activation of the AKT/mTOR pathway is frequently observed in cancer, promoting unrestricted tumor growth through enhanced protein synthesis and cancer cell metabolism." (PMID 38275415, 2024).
cancer (continued). "The mTOR signaling pathway is aberrantly activated in tumors and controls cancer cell metabolism by altering the activity of various key metabolic enzymes." (PMID 39000273, 2024). "LRP6 acted as a regulator involved in maintaining lipid homeostasis via nutrient-sensing mTOR pathways while promoting aberrant lipid lipogenesis and regulating fatty acid synthesis in cancer cells." (PMID 38250152, 2024). "For example, the PI3K/AKT/mTOR pathway is overactivated in cancer, and it is well known that this pathway activates S6K1." (PMID 39408794, 2024). "Recent studies have shown that disruption of mitochondrial functions can lead to Akt-mTOR inactivation in different cancer cells." (PMID 38467612, 2024). "Even though mTORC1 is a well-studied multiprotein complex essential for cancer cell survival, proliferation, and growth, biomarkers predicting patient responses to mTOR inhibitors are still largely missing." (PMID 38197697, 2024). "Its intricate relationship with mTOR highlights its significance in aging and disease processes, making it a compelling focus of research in the field of geroscience and cancer biology." (PMID 38463143, 2024). "Several tumor-related pathways were identified, such as Proteoglycans in cancer, mTOR signaling pathway, FoxO signaling pathway." (PMID 39169938, 2024). "CARMN mediates its anti-cancer effects through the inhibition of the Akt-mTOR and MAPK signaling pathways, as well as the suppression of autophagic flux." (PMID 39558374, 2024). "Multiple studies have shown that targeting mTOR complexes is an important method for cancer treatment research." (PMID 38288377, 2024). "We demonstrate that cancer derived EV regulate cellular metabolism and protein synthesis in acceptor cells through increased activation of mTOR and AMPKα." (PMID 39001708, 2024). "The PI3K/AKT/mTOR signaling pathway—one of the most common over-activated pathways in human cancers—is abnormally altered in nearly 70% of BC." (PMID 38630392, 2024). "Strikingly, we found that genes with the highest network scores defined well-established cancer-related pathways, such as the Myc, mTOR, and WNT/β-Catenin pathways, as well as pathways related to cell cycle and apoptosis." (PMID 39657701, 2024). "Aberrantly activated PI3K/Akt/mTOR signaling is involved in the metastasis of cancers, while inhibition of PI3K/Akt/mTOR can lead to EMT reverse and reduced metastasis." (PMID 39092293, 2024). "Rapamycin has received considerable attention in various fields, such as cancer, antiaging, and infection, due to the multifunction of mTOR in cells." (PMID 38334661, 2024). "Everolimus also targeting mTOR directly showed good results in preclinical studies against several cancers." (PMID 38474109, 2024). "A study suggests that mTOR, overexpressed or hyperactivated in several cancer types, reduces autophagy and increases cancer cell survival." (PMID 39056768, 2024). "In fact, in this resistant cancer cell population, the activation of the mTOR pathway increases chemosensitivity in vitro and in vivo, hence demonstrating the variety of effects signaling pathways can elicit." (PMID 39339243, 2024). "SLC7A5 facilitates cancer initiation and progression by mediating the transport of amino acids and modulating the mTOR signaling pathway." (PMID 39610830, 2024). "The role of the ERMP1 protein in cancer proliferation and progression through the PI3K/AKT/mTOR/β-catenin signaling pathways has been identified as a promising therapeutic strategy for treating various types of cancer." (PMID 38785548, 2024). "The PI3K/AKT/mTOR signaling pathway is known to facilitate the proliferation of cancer cells, and it has been observed that metformin possesses the ability to impede the activity of this pathway." (PMID 39101145, 2024). "The PI3K/AKT/mTOR pathway is a master regulator of cancer cell signaling, which leads to cell growth, invasion, migration, apoptosis, and glucose metabolism." (PMID 38791386, 2024).
cancer (continued). "The combination of PI3K and mTOR inhibitors represents a dual blockade approach that effectively suppresses signaling cascades in promoting cancer cell growth." (PMID 38172946, 2024). "The anti-cancer effects of metformin are attributed to mechanisms such as mTOR inhibition and synergistic effects with chemotherapy and radiotherapy." (PMID 38474224, 2024). "The activation of the mTOR signaling pathway contributes to the progression of different types of cancer, including OS." (PMID 38288377, 2024). "For this reason, selective mTOR inhibitors are under evaluation in clinical trials on different cancers." (PMID 38915098, 2024). "As a result, the mEAK-7-mediated mTOR-DNA–PKcs complex was shown to be a key regulator in human cancer cells, acting through the S6K2 axis." (PMID 39770519, 2024). "The study suggests metformin inhibits EC cell growth and enhances sensitivity to 5-FU by targeting cancer stem cells and mTOR pathway components, supporting its potential benefits for EC patients in combination therapies." (PMID 38474224, 2024). "Reduced levels of adiponectin result in unchecked mTOR regulation and enhanced lipid metabolism, which together promote cancer proliferation and progression." (PMID 39596205, 2024). "Better understanding of nuclear mTOR signaling has the potential to lead to novel therapies against cancer and other growth-related diseases." (PMID 38727317, 2024). "By inducing the degradation of multiple client proteins, PU-H71 disrupts critical signaling pathways such as MAPK, PI3K/Akt, JAK/STAT, EGFR, and mTOR, which are essential for cancer cell survival, proliferation, and metastasis." (PMID 39564119, 2024). "Drugs that target Aurora A kinase as a treatment for cancer can lead to activation of the PI3K/AKT/mTOR pathway and ultimately resistance to treatment." (PMID 38672538, 2024). "Our identification of SGOC as a potentially novel mechanism of BET + mTOR inhibitor synergy stands in contrast to results from other cancers treated with this combination." (PMID 38060314, 2024). "This is in accordance with other data demonstrating the reversible effect of resveratrol on multidrug resistance in cancer cells by suppressing mTOR and nuclear factor erythroid 2-related factor 2 activation through the acceleration of p62 degradation." (PMID 38474838, 2024). "Specifically, targeting the mammalian target of the rapamycin (mTOR) pathway with miRNAs has shown promise in improving the effectiveness of radiotherapy (RT), a common cancer treatment." (PMID 38965615, 2024). "The PI3K/AKT/mTOR signaling pathway plays a significant role in normal physiological processes and in the development and progression of various diseases, including cancer." (PMID 38381215, 2024). "With the mechanistic target of rapamycin (mTOR) signaling pathway enhancing the migration and metastasis of cancer cells, several mTOR inhibitors such as everolimus and temsirolimus are investigated in combinational therapy to treat PC." (PMID 39339243, 2024). "The combination of PI3K inhibitors and mTOR inhibitors has demonstrated encouraging outcomes in cancer treatment." (PMID 38172946, 2024). "These enrichments included, for example, pathways in cancer (p = 0.240), the TGFβ signaling pathway (p = 0.260), and the mTOR signaling pathway (p = 0.260)." (PMID 39594632, 2024). "The function of SLC7A5 also activates the AKT/mTOR pathway which then mediates the radioresistance ability of cancer cells." (PMID 38705513, 2024). "Recent studies have focused on the regulatory function of mTOR signaling in immunological features in several pathological conditions, including cancer." (PMID 38791040, 2024). "Although the PI3K/AKT/mTOR pathway has been extensively investigated in cancer, few studies have been conducted on CSCs." (PMID 39469631, 2024).